CETN1 (centrin 1)
Description:
Plays a fundamental role in microtubule-organizing center structure and function. Plays a role in sperm cilia formation (By similarity).
Synonyms: CEN1; CETN
Tractability: PROTAC: ubiquitination databases record sites on it.
Gene: Protein-coding gene on chromosome 18 (580,380 to 582,114, forward strand). Ensembl gene ENSG00000177143.
Subcellular location: Cytoplasm, cytoskeleton, microtubule organizing center, centrosome; Cell projection, cilium
Subcellular location (Human Protein Atlas): Flagellar centriole; Nucleoplasm; Mid piece; Principal piece
Pathways (Reactome):
Autophagy: Aggrephagy; Chaperone Mediated Autophagy; Late endosomal microautophagy
Gene Ontology:
Molecular function: protein binding; calcium ion binding; G-protein beta/gamma-subunit complex binding; heterotrimeric G-protein binding; microtubule binding
Biological process: centriole replication; microtubule cytoskeleton organization
Cellular component: centriole; centrosome; nucleoplasm; sperm midpiece; sperm principal piece; spindle pole; cytosol; nucleus; photoreceptor connecting cilium; cilium; microtubule organizing center
Genetic constraint (gnomAD): Loss-of-function variants: 8 observed, 9.06 expected, observed/expected ratio (o/e) 0.88, 90% interval 0.52 to 1.57. That is too few expected variants to judge how well the gene tolerates losing a copy. Missense variants: 215 observed, 236.31 expected, observed/expected ratio (o/e) 0.91, 90% interval 0.81 to 1.02. Synonymous variants: 99 observed, 96.43 expected, observed/expected ratio (o/e) 1.03, 90% interval 0.87 to 1.21.
Homologues: Orthologues: chimpanzee CETN1 (97% identical), macaque CETN1 (94% identical), dog CETN1 (93% identical), guinea pig CETN1 (91% identical), mouse Cetn1 (91% identical), rabbit CETN1 (91% identical), rat Cetn1 (90% identical), tropical clawed frog cetn2 (83% identical), pig CETN1 (82% identical), zebrafish cetn2 (80% identical), Drosophila melanogaster CG17493 (69% identical), Drosophila melanogaster CG31802 (56% identical), and 6 more. Paralogues in human: CETN2 (83% identical), CETN3 (52% identical), CALM1 (46% identical), CALM2 (46% identical), CALM3 (46% identical), CALML3 (42% identical), CABP2 (36% identical), CALML5 (35% identical), CABP4 (33% identical), CALML6 (33% identical), CABP1 (32% identical), CABP5 (31% identical), and 8 more.
Diseases named in the same sentence as CETN1 in open-access papers:
CETN1 is named in the same sentence as 15 diseases in open-access papers, as found by Europe PMC text mining. Sharing a sentence is not in itself a finding about the gene and the disease. The quoted sentences say what the papers report.
cancer of the prostate (2 papers, 2013 to 2019). "Using q-PCR, CETN1 expression is shown to be highly up-regulated in cancer of the prostate and in pancreatic xenografts." (PMID 24252580, 2013). "This work suggests that CETN1 is a novel CTA with expression in cancer of the prostate and pancreas." (PMID 24252580, 2013). "Furthermore, based on its expression pattern in normal testis and tumor tissues and its regulation by DNA hypomethylation, we identify CETN1 as a novel member of a growing family of proteins called Cancer/Testis Antigens (CTAs) up-regulated in prostate cancer (PCa) and pancreatic cancer." (PMID 24252580, 2013).
male infertility (2 papers, 2021 to 2025). The inability of the male to effect fertilization of an ovum after a specified period of unprotected intercourse. "Additional corroboration of our results has been observed in other centriole gene knockout experiments in D. melanogaster where the depletion of centriolar proteins such as CETN1 results in male infertility." (PMID 40294089, 2025). "Previously knockout of such types of retrogenes, including Cetn1, Cstf2t, Pgk2 and Rpl10l, always resulted in spermatogenic abnormalities and male infertility." (PMID 34249105, 2021).
Obesity (2 papers, 2019 to 2021). Accumulation of substantial excess body fat. "Obesity is associated with declines in the abundances of CETN1 and CSPP1 and affect sperm morphology in mice and relevant clinical samples." (PMID 34330296, 2021). "Herein, this is the first report describing a relationship between CETN1 expression levels and obesity-associated asthenozoospermia and teratozoospermia." (PMID 31651332, 2019). "Even though the function of CENT1 is known in spermatogenesis, there is scant information regarding the role of CSPP1 and CETN1 in obesity associated teratozoospermia." (PMID 31651332, 2019). "Obesity is associated with declines in the CETN1 and CSPP1 abundance and compromise of both sperm morphology in mice and relevant clinical samples." (PMID 31651332, 2019). "The results show that the declines in centrosome and spindle pole associated protein 1 (CSPP1) and Centrin 1 (CETN1) expression levels in mice fed a HFD may contribute to obesity-induced male subfertility." (PMID 31651332, 2019). "Taken together, these data suggest that regionally delimited expressions of CSPP1 and CETN1 are strongly associated with spermiogenesis and maintenance of normal sperm morphology whereas its deficiency in sperm may contribute to obesity-associated asthenozoospermia and teratozoospermia." (PMID 31651332, 2019). "Additionally, immunoblot analysis showed that CSPP1 and CETN1 contents were significantly reduced in sperm from overweight or obesity males compared with that from normal males, which is in agreement with the results in the mice of HFD group." (PMID 31651332, 2019).
breast carcinoma (1 paper, 2016). "Knockdown of CETN1 inhibits breast cancer cell proliferation." (PMID 27597120, 2016).
cutaneous leishmaniasis (1 paper, 2024). Leishmaniasis affecting the skin. "Indeed, attenuated Leishmania lacking the centrin 1 gene is being intensively explored in the context of vaccination against visceral and cutaneous leishmaniasis." (PMID 38543944, 2024).
lung carcinoma (1 paper, 2023). "HOP62 and ED1 lung cancer cells were each treated with CYC065 or vehicle as a control and then immunostained independently for γ-tubulin and Centrin 1 along with DAPI staining for centriole stoichiometry scoring." (PMID 38031910, 2023).
pancreatic cancers (1 paper, 2013). "In this work, we discovered that Centrin 1 (CETN1) which is found in the centrosome of all eukaryotes, may be a member of this group and is highly expressed in prostate and pancreatic cancer." (PMID 24252580, 2013).
teratozoospermia (1 paper, 2019). "Meanwhile, low CSPP1 and CETN1 expression levels are associated with human astheno-teratozoospermia in clinical samples." (PMID 31651332, 2019).
visceral leishmaniasis (1 paper, 2023). A severe form of leishmaniasis characterized by irregular bouts of fever, substantial weight loss, swelling of the spleen and liver, and anemia (which may be serious). "In this study, we evaluated a vaccine against visceral leishmaniasis consisting of a double genetically deficient Leishmania donovani for the Centrin 1 gene and macrophage migration inhibitory factor (LdCen−/−MIF−/−)." (PMID 37147351, 2023).
cancer (3 papers, 2013 to 2025). A tumor composed of atypical neoplastic, often pleomorphic cells that invade other tissues. "Here, we characterize the human CETN1 gene as a cancer associated gene." (PMID 24252580, 2013). "Some IDPs were also discovered to be cancer biomarkers, such as CETN1 in prostate and pancreatic cancer." (PMID 41271784, 2025). "Centrin1 (CETN1) is a novel member of Cancer/Testis Antigens, with a 25‐fold increase of CETN1 gene expression in PDX from PDAC patients." (PMID 31309741, 2019). "Additionally, like most CTAs, CETN1 appears to be an intrinsically disordered protein which implies that it may occupy a hub position in key protein interaction networks in cancer." (PMID 24252580, 2013). "In our study, we targeted CETN1, which by virtue of being a Cancer/Testis Antigen (CTA), is not expressed in healthy tissues other than testes." (PMID 31309741, 2019).
tumor (3 papers, 2016 to 2019). "In conclusion, we report the generation of novel highly specific antibodies to CETN1, their evaluation in patients’ tumor microarrays, their utility in radioimmunoimaging, and effectiveness in RIT of experimental PDAC." (PMID 31309741, 2019). "Here, we report the generation of highly specific for CETN1 antibodies and their evaluation in patients’ tumor microarrays and for radioimmunoimaging and radioimmunotherapy (RIT) of experimental PDAC." (PMID 31309741, 2019). "Additionally, effective tumor responses from CETN1 targeted radiation might not even require the administration of high radionuclide doses, since the radiolabeled antibody will not be “wasted” by targeting the antigen on the healthy tissue rather than concentrate in the tumor." (PMID 31309741, 2019).
CETN1 also shares sentences with these, for which no sentence is quoted: asthenozoospermia (1 paper); infection (1); Infertility (1); osteosarcoma (1).